MIR548H3 (microRNA 548h-3)
Synonyms: hsa-mir-548h-3; MIR548H-3; MIRN548H3
Gene: MicroRNA gene on chromosome 17 (13,543,529 to 13,543,646, reverse strand). Ensembl gene ENSG00000221698.
Gene Ontology:
Biological process: miRNA-mediated post-transcriptional gene silencing
Cellular component: RISC complex
Homologues: Paralogues in human: MIR548Z (66% identical), MIR548K (64% identical), MIR548X2 (63% identical), MIR548AZ (62% identical), MIR548AA1 (60% identical), MIR548AY (60% identical), MIR548AN (58% identical), MIR548N (57% identical), MIR548F1 (56% identical), MIR548P (56% identical), MIR548F3 (55% identical), MIR548AH (54% identical), and 13 more.